IL1A (interleukin 1 alpha)
Diseases named in the same sentence as IL1A in open-access papers (continued):
Sharing a sentence is not in itself a finding about the gene and the disease.
tumor (continued). "Hence, combining IL1A with other anti-tumor medications could present a novel approach to KIRC treatment." (PMID 40612864, 2025). "Notably, blockade of IL-1α signaling delayed tumor growth and enhanced NK cell-mediated immunity." (PMID 41181123, 2025). "However, the role of IL-1α in promoting antitumor immunity remains unclear and may be tumor specific, as studies suggest that it can act in both a pro- and antitumor manner." (PMID 38391959, 2024). "On the other hand, 4T1 IL-1α KO-derived tumors were characterized by less inflammation and an abundance of antigen-presenting and cytotoxic cells, which could be responsible for the inhibition of tumor growth." (PMID 38612760, 2024). "In the absence of anti-tumor immune cells, TNBC cells could grow unimpeded, with IL-1α KO cells fully realizing their increased aggressive potential, which was observed in the in vitro experiments, and exceeding the rate of tumor progression achieved by 4T1/WT cells." (PMID 38612760, 2024). "However, the secreted form of IL‐1α has been shown to facilitate tumour invasion and angiogenesis." (PMID 39602465, 2024). "Moreover, the overexpression of PD-L1 in tumor cells can be due to the activation of signal traducers induced via oncogenic pathways, as has been described in melanoma, with oncogenic BRAF(V600E) signaling inducing IL-1α/β production, with a subsequent upregulation of PD-L1 in the tumor stroma." (PMID 37834467, 2023). "However, there are only a few reports on the effect of tumor-secreted IL-1α on macrophages." (PMID 37998338, 2023). "Genetic deletion of Il1a/b is associated with decreased recruitment of lymphoid cells and loss-of-interferon signaling in various immune populations and subsets of malignant cells and is associated with decreased survival time of PDGFB-driven tumor-bearing mice." (PMID 37733448, 2023). "The gene IL-1A expresses interleukin IL-1A, a pro-inflammatory cytokine produced by monocytes and macrophages, released in response to cell injury, which may influence proliferation, angiogenesis, and tumor invasion, among other carcinogenic events." (PMID 36833388, 2023). "Therefore, MPs based on CPH:SA formulations may be promising as delivery vehicle for IL‐1α and other cytokines to achieve safe, effective anti‐tumor responses for cancer patients." (PMID 37206237, 2023). "The antitumorigenic immune components of tumor microenvironment are natural killer (NK) cells, dendritic cells (DC), cytotoxic T lymphocytes (CTLs), and M1 tumor-associated macrophages (M1 TAMS) secreting mainly proinflammatory cytokines like IL-1β, IL-1α, IL-6, IFNγ, TNFα etc.." (PMID 36496977, 2022). "In addition, further analysis revealed that in metastatic HSCs, the expression of TERT was significantly decreased, while the expression of IL1A was significantly increased, suggesting that cuproptosis might play an essential role in tumor metastasis." (PMID 35875097, 2022). "Notably, IL-1α stimulated tumor-induced osteoclastogenesis and RANKL-induced osteoclastogenesis." (PMID 36614130, 2022). "It was noticed that overexpression of IL-1α may have anti-tumor effects." (PMID 36237303, 2022). "In addition, this study demonstrated that knockdown of LSR could increase the expression of pro-oncogenic genes, such as interleukin 1 alpha and endothelin 1, which could contribute to tumor initiation and progression." (PMID 35586495, 2022). "Induction of IL1A could promote proliferation, angiogenesis, and metastasis of tumor cells." (PMID 35432539, 2022). "Importantly, reversal of iCAF polarisation via IL-1α inhibition seemingly sensitised tumours to radiotherapy and therefore may be a useful combination therapy." (PMID 36313650, 2022). "Tumor-associated leukocytes isolated from lymph node+ BC patients secreted 2- to 5-fold more cytokines than lymph node- patients, with the most increased cytokines being thymus and activation-regulated chemokine (TARC/CCL17), IGF-1, IL-3, TNF-β, IL-5, G-CSF, IL-4, and IL-1α." (PMID 34602858, 2021).
tumor (continued). "In contrast, tumor-infiltrating myeloid-derived suppressive cells (MDSCs) hinder senescence induction and spread through the secretion of interleukin 1 (IL-1) receptor antagonist within tumor microenvironment, and thereby interfering with IL-1α signaling pathway." (PMID 33330071, 2020). "The skin inflammatory process promotes skin dryness, induces infiltration of inflammatory cells, increases skin thickening and stimulates the membrane receptors of keratinocytes which promotes the release of various inflammatory mediators such as TNFα, IL-8, IL-1α, IL-6 and IL-12." (PMID 33371334, 2020). "Taken together, these data suggest that MOv18 IgE may support TAM populations with mature phenotypes and hybrid M1/M2 features that are able to enter the tumour, trigger sustained immune activating pathways and secretion of IL-10, TNFα, MCP-1 and IL-1α in tumour-bearing lungs." (PMID 31544825, 2019). "IL-1B and IL-1A may both play roles in tumour formation and progression to metastasis." (PMID 29760166, 2018). "However, tumor growth was significantly delayed in mice bearing tumors expressing shIL-1α as compared to mice bearing tumors expressing scrIL-1α, supporting a paracrine role for IL-1α in prostate tumorigenesis." (PMID 29502208, 2018). "SMAD7 might represent a target for inhibition of IL-1α induced tumor stroma interactions." (PMID 27473228, 2016). "Overexpression of miR-22 in male tumor adjacent tissue was associated with downregulated ERα expression, potentially by attenuating the protective effect of estrogen and causing increased IL-1α expression and STAT3 and IL-1α involved in inflammation and stemness inducible of HCC progression." (PMID 26503703, 2015). "Activated macrophages have the capacity to secrete pro-inflammatory IL-1 cytokines, and since inflammation is crucial for gp130757FF tumor development we assessed whether activated macrophages contribute to elevated IL-1α and IL-1β expression in 30 week old gp130757FF mice." (PMID 25528766, 2015). "Thus, proliferating in the context of significantly reduced numbers of NK and CD8 cells, the malignant population of CD16/32HI LGLs within IL-15−/− tumors expressed elevated IL-1α and IL-1α-regulated transcripts and recruited activated tumor-infiltrating neutrophils." (PMID 24416335, 2014). "However, in some tumor cells, active secretion of IL-1α is observed." (PMID 24734023, 2014). "Thus, in the tumor microenvironment, carcinoma-derived IL-1 (IL-1α and IL-1β) activates mesenchymal stem cells (MSCs) to produce PGE2 and other cytokines, such as IL-6, IL-8, Gro-α, and RANTES that in turn act on the carcinoma cells and induce activation of β-catenin and transition into CSCs." (PMID 23847618, 2013). "Elevated cytokine levels, including IL1α, TNFα, IL6, IL10, IL17, and IL12, represent the rejuvenation of tumor immunity in response to combination ICI." (PMID 40313772, 2025). "IL-1α plays a capital role in CRC and more specifically in the tumour microenvironment (TME), promoting angiogenesis, immune evasion, and tumour progression." (PMID 39820336, 2025). "Aging cells secrete inflammatory factors (such as IL-1α and IL-6) through SASP, which intensifies local inflammatory response and promotes the proliferation of tumor cells by activating NF-κB and STAT3 pathways." (PMID 40951350, 2025). "The upregulation of key mediators such as TNF, IL1A/B, INFG, INFA2, and TGFB1 in tumor-educated immune cells suggests a shift toward a pro-inflammatory yet immunosuppressive phenotype." (PMID 41514627, 2025). "First, we examined the effect of IAPi on the expression of known factors involved in LKB1-mut tumor-immune responsiveness, including STING, IL-1α, IL-6, G-CSF, and PD-L1, 9,28,29,32." (PMID 40057483, 2025). "Using next‐generation sequencing, we found that in tumor tissues with high CCL24 expression, iCAF markers (IL1A, IL1B, IL6, CXCL1, and CXCL5) were significantly highly expressed, indicating high infiltration of iCAFs in the TME." (PMID 40397411, 2025).
tumor (continued). "A significant correlation was found between tumor height and several cytokines, including β-NGF, CTACK, Eotaxin, IFN-γ, IL-16, IL-1α, IL-1ra, IL-6, IL-8, M-CSF, MCP-1, MIP-1α, and SCGF-β." (PMID 41048959, 2025). "In contrast, IL1A, IL11, and IL27 were downregulated, indicating their potential function as tumor suppressors." (PMID 40612864, 2025). "Consistent with the reduction of IL-1α, CCL2, and CCL3 in SHP2-silenced tumors, IHC revealed that tumor-infiltrating CD45+ hematopoietic cells and F4/80+ macrophages were significantly reduced in SHP2-silenced B16F10 tumors compared with controls." (PMID 40131370, 2025). "Differential expression analysis revealed that CASP4, CHMP4B, ELANE, IL-1A, and TNF were significantly upregulated in tumor samples (p < 0.05)." (PMID 40538398, 2025). "Significant differences in expression were observed for TNF-α, TGF-β, IL-1α, IL-1β, and IL-12 between PeIN and early (I + II) and advanced-stage (III + IV) tumours (Kruskal–Wallis test, p < 0.05)." (PMID 41465261, 2025). "The levels of IL1A and IL6 were higher in patients with advanced stages than in those with tumor stage 1." (PMID 40860188, 2025). "Consistent results were achieved for all 94 paired tumour–normal samples for TNF-α and IFN-γ, for 93 paired samples for TGF-β1 and IL-1α, for 90 paired samples for IL-1β and IL-12, and for 87 paired samples for IL-2 and IL-6 expression." (PMID 41465261, 2025). "We found that, compared to normal tissues, BAX, CHMP2A, CHMPB, IL1A, IL1B, and VPS24 were more strongly expressed in the cytoplasm and nucleus of tumor tissues." (PMID 39744500, 2025). "Based on this approach, TNF-α, IL-6 and IL-12 showed the highest discriminative ability between tumour and normal tissue (AUC 0.76, 0.65 and 0.65, respectively), while TGF-β1 and IL-1α yielded AUC values close to 0.5, indicating limited diagnostic value." (PMID 41465261, 2025). "While the top three KLF4-assocaited genes correlated with a tumor stimulatory effect for several tumors were CX3CL1, TNFRSF4, and IL1A." (PMID 40299916, 2025). "Immune evasion was evident through upregulation of NFKB1, IFNAR1, TLR4, IL1A/B/R1, and NOS2, facilitating tumour escape from immune surveillance." (PMID 41007296, 2025). "Proinflammatory cytokines such as IL-6, IL-1α, IL-1β and IL1RA are primarily secreted by activated myeloid cells and play critical roles in an anti-tumor immune response." (PMID 38400933, 2024). "Conversely, a negative correlation was observed between the production of interleukin 1 alpha (IL1A) by CAFs and the expression of its receptors—IL1R1, IL1R2, and IL1RAP—on tumor cells." (PMID 39519201, 2024). "IL1A, a pivotal inflammatory cytokine, is thought to be one of the critical upstream regulators of other SASP-related genes and drives tumor growth and metastasis." (PMID 39267750, 2024). "Pro-inflammatory TAMs express TH1 response-inducing cytokines such as IL1α, IL1β, IL12 and TNFα while pro-tumor TAMs express IL10, CCL8, and CCL22 that are tumor promoting." (PMID 38802355, 2024). "IL1A, exhibiting similarities to IL1B, displayed a tenfold increase in 44% of the tumor samples, though its average normalized count in tumors was notably lower." (PMID 38979413, 2024). "In contrast, tumor cells in a persistent senescent state can release SASP factors, such as the proinflammatory cytokines IL-1α, IL-6 and IL-8, to mediate tumor progression in neighboring cells." (PMID 39342176, 2024). "We identified pro-inflammatory cytokines (IL1A, IL1B, IL6), and chemokines (CCL3, CXCL2, CXCL3) that promote inflammation-promoted neoplasia." (PMID 38529274, 2024). "CAFs are a relevant cell population in the PDAC stroma that express IL-1R1, and when stimulated with IL-1α and/or IL-1β, they secrete several pro-tumor cytokines, including TSLP, which is responsible for pro-tumor Th2 inflammation in PDAC." (PMID 39125655, 2024).
tumor (continued). "TAMs are also able to release molecules (e.g., TNFa, IL1a, and COX-2) that indirectly contribute to tumor angiogenesis via the induction of a proangiogenic program in tumor cells." (PMID 39516356, 2024). "These reactions arise from tumor-derived cytokines, including granulocyte colony-stimulating factor (GCSF), granulocyte-macrophage colony-stimulating factor (GMCSF), interleukin-1 alpha (IL-1α), and IL6." (PMID 38792013, 2024). "Mo0 stimulated the release of cytokines and chemokines such as IL6, IL1A, CXCL1, CXCL5, and CCL20, which can induce monocyte recruitment to tumor." (PMID 37675100, 2023). "mRNA expression of 16 soluble factors was quantified with tumor cell density, and we found that IL-8 was the only factor with fluctuations (HGF, IL-1A, and IL-12B expression levels were extremely low)." (PMID 36932390, 2023). "To determine the roles of IL1α, IL1β and IL8 in promoting tumor growth, we knocked down the expression of these three genes using shRNAs and measured the tumor size after 42 days." (PMID 37551997, 2023). "Tumor-released IL-1α accelerates the progression of HCC by promoting MDSCs recruitment and infiltration in spleen and tumor via CXCR2 and suppressing the capacity of CTL." (PMID 37217620, 2023). "Pharmacological antagonizing Il1 signaling locally in tumor-bearing mice extended survival time and decreased TAM infiltration, which was opposite of what was observed with Il1a–/–;Il1b–/–;Ntv-a mice." (PMID 37733448, 2023). "PAR1CAR-T cells secrete proinflammatory cytokines and chemokines, including TNF-α, IFN-γ, IL-1α, IL-4, IL-6, IL-17A, and GRO, upon encountering PAR1 antigens that exhibit potent cytolytic capacities against PAR1-expressing tumor cells." (PMID 37667257, 2023). "Similar to the results obtained from the lung colony formation experiment, knockdown of IL1β in the 231‐GFP cells also had less effects than knockdowns of IL1α and IL8, resulting in the reduction of the tumor size by 39% and tumor weight by 21%." (PMID 37551997, 2023). "Meanwhile, exosomal miR-101 also affects macrophage function by suppressing IL1A and IL6 expression, which reduces growth and macrophage tumor infiltration in vivo." (PMID 38002256, 2023). "Pro-inflammatory cytokines, such as IL-1α, IL-1β, IL-6, and TNF, showed higher amounts in the saliva of patients with OSCC, indicating the involvement of the inflammatory environment in tumor progression." (PMID 37686462, 2023). "Considering the strong effect of combined Il1a and Il1b loss on MCP levels in tumors together with the strong effect on monocyte recruitment shown in scRNA-Seq data, we sought to determine whether genetic deletion of both Il1a and Il1b would further extend survival of tumor-bearing mice." (PMID 37733448, 2023). "Upregulation of procancer genes (Spp1, Igf1, Plgs2, Plau, Ctsk, Areg, Hbegf, Il1a, Ilb) was found in TAM-WT compared with TAM-KO, and this aligns with the observation that CL-11 is required for tumor cell proliferation, tumor growth, and angiogenesis." (PMID 36883567, 2023). "In fact, blocking IL1α signalling has been shown to revert CAF inflammatory phenotype, thus reducing tumor growth and chemoradiotherapy resistance in rectal cancer." (PMID 36757577, 2023). "In such manner, studies were conducted in which IL-1α was shown to be regulated by HIF-1α, and a change in HIF-1α expression altered the tumor-promoting effect of IL-1α." (PMID 37007020, 2023). "We earlier reported that Notch, IL-1α, leptin, and VEGF/VEGFR-2 expressions were higher in human CRC and tyroid tumor tissue compared to normal tissue." (PMID 38152619, 2023).
tumor (continued). "For instance, the pro‐inflammatory gene markers IL1A/B were overexpressed in the peri‐tumor tissue, whereas IL1RN was significantly upregulated in the tumor core, which is an inhibitor of IL1A/B." (PMID 37434432, 2023). "Macrophages induce ROS elevation and increase expression of IL1α, which is bound to IL1R1 to activate ERK1/2, MKK4, and NF‐κB‐mediated signaling pathways to facilitate tumor growth and metastasis." (PMID 37551997, 2023). "The PGF2 tumor phenotype has elevated CCL2, IL6, IL1A, and IL1B, all of which are secreted by uterine smooth muscle cells treated with PGF2." (PMID 36834607, 2023). "The study further demonstrates that Schwann cells can induce malignant progression of tumor cells and CAFs by releasing MDK and IL-1α." (PMID 37524695, 2023). "The scoring signature is constructed by three genes (IL1A, NT5E, and TLR7), whose expression in the tumor is significantly higher than normal both in the TCGA cohort and our PKUCH cohort." (PMID 36979463, 2023). "The overexpression of miRNA-101 or enriched exosome uptake by macrophages suppresses IL1A and IL6 expression by targeting CDK8, whereas injecting miR-101 into xenografted tumors reduced growth and macrophage tumor infiltration in vivo." (PMID 38002256, 2023). "Necrotic and necroptotic cancer cells can promote tumour development by recruiting TAMs to the TME and releasing regulatory cytokines, such as IL1α, that promote cancer cell proliferation." (PMID 36497148, 2022). "We also identified unique signatures in tumour samples after VV-αCEA TCE treatment, including increased levels of CCL1, IFNγ, IL-1a, IL-1b, TIMP-1, and TREM-1." (PMID 36405739, 2022). "Using value of IOD, quantification of immunohistochemical analysis showed that protein expressions of CYBB, IL1A, IL1B, and SLC25A5 were significantly higher in CESC tissues than in adjacent non-tumor tissues (P < 0.001)." (PMID 36253777, 2022). "Lysates of MTX-treated 9464D tumors displayed a more than 2.5-fold increase of IL1a, CXCL16, FLT3L, CX3CL1 and IL1RA, and a more than 1.5-fold increase of CXCL10, CXCL5, CCL5 and CXCL9 compared to control tumor lysates." (PMID 36397148, 2022). "Three genes (ELANE, NLRP7, and CASP5) were downregulated, whereas seven others (GSDMC, IL1A, NOD2, GZMB, GSDMA, IL1B, and PLCG1) were overrepresented in the tumour group." (PMID 35087586, 2022). "For instance, in melanoma patients, IL‐1α induced the MyD88‐dependent activation of the NF‐κB and MAPK pathways as well as an increase in ROS production, promotes tumour progression." (PMID 35344301, 2022). "Compared with the Puget 0 grade tumor group, the expression of IL1A and IL6 in the Puget 2 tumor group was significantly increased." (PMID 36389809, 2022). "Important immunological checkpoints involved in tumor immune escape include CD274, IL1B, IL1A, PDCD1, PDCD1LG2, and SIRPA." (PMID 35401746, 2022). "IL1A and IL6 are two crucial inflammatory cytokines in macrophages, playing important roles in tumor development." (PMID 36071472, 2022). "In the present study, we investigated the role of the SASP factors IL1A and IL1B for tumor cell killing by IR in the context of irradiation-induced senescence in vitro." (PMID 35530351, 2022). "Conversely, when used as a treatment, IL-1α in combination with existing EGFR inhibitor therapy, cetuximab, was found to effectively induce T cell dependent anti-tumor immune response." (PMID 33430381, 2021). "First, we studied how IL1A controls the tumor growth and invasion of TNBC cells and how ETL regulates the level of IL1A expression." (PMID 34203721, 2021). "The overexpression of IL1A can, in turn, stimulate the transcription of growth factors such as MMP1 or VEGFA, both found upregulated in our tumor samples, possibly creating a proper environment for carcinogenesis." (PMID 34638231, 2021).